CYP26A1 (cytochrome P450 family 26 subfamily A member 1)
Diseases named in the same sentence as CYP26A1 in open-access papers (continued):
Sharing a sentence is not in itself a finding about the gene and the disease.
cancer (22 papers, 2005 to 2025). A tumor composed of atypical neoplastic, often pleomorphic cells that invade other tissues. "Another potential target for small-molecule compounds is CYP26A1, which is considered a promising therapeutic candidate due to its critical role in retinoid metabolism and its association with cancer cell resistance." (PMID 40807478, 2025). "High expression of CYP26A1 is associated with several cancers such as breast, head and neck, colorectal and ovarian." (PMID 28651018, 2017). "Such strong CYP26A1 expression was significantly associated with the primary tumor stage of carcinomas (pT) and the pathological tumor-node-metastasis (pTNM) stage in HNC." (PMID 25294402, 2014). "CYP26A1 is a methylation marker of PCs associated with ERG-positive cancers." (PMID 28651018, 2017). "Although the effects of nuclear or cytoplasmic CYP26A1 in cancer remain unknown, the altered location of CYP26A1 potentially associates with the regulation of unidentified signaling pathways." (PMID 25294402, 2014). "Furthermore, CYP26A1 overexpression was significantly associated with the primary tumor stage of carcinomas and pTNM stage, suggesting that CYP26A1 was primarily correlated with primary tumor growth in HNC patients." (PMID 25294402, 2014). "Therefore, the association between CYP26A1 and the immune cells might be partly responsible for its promoting-cancer effect." (PMID 35707714, 2022). "CYP26A1, which is a major enzyme involved in the catabolism of retinoic acid, has been identified as a biomarker in multiple cancers." (PMID 37886241, 2023). "EBBP acts to derepress the transcription of RARb2 (retinoic acid receptor β2) and CYP26A1 (cytochrome P450 family 26 subfamily A member 1), by modifying histone acetylation in retinoid-resistant cancer cells." (PMID 36261847, 2022). "Treatment with 100 μM arecoline resulted in a decreased expression of CYP26A1 mRNA in CAL 27 cancer cells (p < 0.05) compared with the untreated control group." (PMID 33233443, 2020). "These qPCR results confirmed a similar distribution of gene expression; overexpression of CYP1B1, CYP7A1, CYP17A1, and CYP19A1, and repression of CYP1A2, CYP2B6, CYP2C19, and CYP26A1 was observed in cancer tissues." (PMID 31258835, 2019). "In the cancer tissue of number 4, a slightly decreased expression of CYP26A1 and increased expression of CYP26B1 were found." (PMID 25839051, 2015). "CYP26A1 expression was lower in the cancer tissue of number 7 compared with its adjacent tissue, but the expression of CYP26B1 was higher in the cancer tissue than in the adjacent tissue." (PMID 25839051, 2015). "This study also suggested that increasing concentrations of endogenous RA and CYP26A1 inhibitors will be applied in the future treatment of cancer or novel therapies for skin diseases." (PMID 25839051, 2015). "While using retinoids to treat other cancers has shown limited success, therapeutically inhibiting CYP26A1, as we have shown herein, to reduce RA metabolism may prove useful in designing approaches to promote the differentiation of CSCs with retinoids." (PMID 38254755, 2024). "Previous studies have reported elevated levels of CYP26A1 in a wide variety of cancers." (PMID 25294402, 2014). "To date, the relevance of elevated CYP26A1 expression in human cancers has yet to be clarified." (PMID 25294402, 2014). "Indeed, enhanced RA metabolism and elevated CYP26A1 levels have been observed in various types of cancer." (PMID 25294402, 2014). "However, the relevance of elevated CYP26A1 expression in human cancers remains to be clarified." (PMID 25294402, 2014). "This structural combination allows the design of compounds capable of modulating key cancer-related targets such as S1PR1, CYP26A1, APN/CD13, and eEF2K, supporting the structure–activity relationship approach." (PMID 40807478, 2025).
cancer (continued). "An explanation could come from the finding that RA metabolizing enzyme CYP26A1, which metabolizes RA, decreases RA signaling, and impedes cell differentiation, is also overexpressed in CRC cells and other cancer types." (PMID 39796106, 2024). "The risk of developing oral malignant disorders may be related to the functionally relevant combined effects of SNPs such as those in CYP26A1, CYP26B1, and CYP26C1 within and between different cancer pathways." (PMID 31465460, 2019). "Since both RARβ2 and CYP26A1 gene expression was not detectable without aRA treatment in all aRA-sensitive and -resistant cancer cells tested, we did not carry out RARβ2 siRNA transfection experiments without treatment with aRA." (PMID 16012519, 2005). "Our data showed clearly that exogenous overexpression of RARβ2 did not induce CYP26A1 expression in the absence of RA ligand, even in RA-sensitive cancer cells." (PMID 16012519, 2005). "The exact function and expression pattern of CYP26A1 in cancer have not been elucidated." (PMID 25294402, 2014). "Thus, it is not surprising that CYP26A1 upregulation results in VAD-associated consequences in the squamous mucosa of the cervix, head, and neck, eventually leading to an increased risk for cancer development and progression." (PMID 25294402, 2014). "DNA demethylation, histone acetylation, and exogenous overexpression of RARβ2 partially restored retinoid-responsive CYP26A1 expression in RA-resistant MDA-MB-231 breast, but not SK-MES-1 lung, cancer cells." (PMID 16012519, 2005).
tumor (22 papers, 2005 to 2025). "In an earlier study, high levels of CYP26A1 mRNA expression were found to be induced by RA in certain human tumor cell lines, further indicating that the RA-inducible RA metabolism may be associated with CYP26A1 expression." (PMID 33233443, 2020). "Alternatively, CYP26A1 overexpression might be directly associated with the cumulative alterations of aberrant signaling, including activation of proto-oncogenes and inactivation of multiple tumor suppressor genes." (PMID 25294402, 2014). "We then investigated the effects of these CYP26A1 inhibitors in combination with agents (Sulindac or Piroxicam) that have anti-tumor activity against APC-mutant tissues." (PMID 38254755, 2024). "We found that the majority of CRC patients expressed an increased level of CYP26A1 in their tumor tissues compared to normal colon tissue from the same patient." (PMID 38254755, 2024). "The anti-proliferative effects of CYP26A1 inhibitors Liarozole and Talarozole were evaluated alone and in combination with Sulindac and Piroxicam, which have anti-tumor activity against APC-mutant tissues." (PMID 38254755, 2024). "Mutation of the APC tumor suppressor gene drives CRC development by constitutively activating WNT signaling, which increases CYP26A1, its enzymatic degradation of retinoids, and decreases RA signaling." (PMID 38254755, 2024). "Previous findings also indicated that a decrease in Cyp26a1 led to an increase in atRA, and atRA was demonstrated to be an antitumour metabolite in several tumour types." (PMID 37997519, 2023). "A significant application performance (area under the curve (AUC) = 0.675; 95% confidence interval (CI) = 0.552–0.798; p = 0.01 < 0.05) was demonstrated by the ROC curve for the mRNA levels of CYP26A1 between tumor and adjacent normal tissues." (PMID 33233443, 2020). "In the assessment of CYP26A1 mRNA, the mRNA levels were used to distinguish the tumor and adjacent normal tissues." (PMID 33233443, 2020). "had shown that the CYP26 inhibitor R116010, co-applied with 13-cis-RA in animals, reduces 13-cis-RA metabolism in the liver, leading to higher levels of serum 13-cis-RA and ATRA, plus greater CYP26A1 transcription in xenografted SH-SY5Y tumours." (PMID 31903789, 2020). "Subsequently, in BQ chewers (n = 28), we compared the expression of CYP26A1 mRNA in human oral sites and pharynx tumor tissues, respectively." (PMID 33233443, 2020). "This was shown to be a result of dramatic decrease in the expression of atRA synthesizing enzymes ALDH1A1 with concomitant increase in atRA degrading enzyme CYP26A1 in intestinal tissues from tumor-bearing compared to tumor-free mice." (PMID 28098786, 2017). "Indeed, in human CRCs, CYP26A1 is significantly overexpressed in tumor tissues compared to normal colon tissues." (PMID 38254755, 2024). "Considering that CYP26A1 is a key enzyme responsible for RA degradation, patients who express lower levels of CYP26A1 should have higher levels of RA in their tumor cells, which should upregulate RA signaling activity and endow CRC patients with better survival." (PMID 38254755, 2024). "CYP26A1 has been shown to be expressed at a constitutively higher level in breast adenocarcinomas which can be selectively inhibited, e.g., by use of a RA metabolism blocking agent R116010, demonstrating an anti-tumour effect in ER+ mouse tumours." (PMID 33809117, 2021). "Upregulation or overexpression of CYP26A1 triggers the signals for cell survival and anti-apoptosis by inducing oncogenes and downregulating tumour suppressor genes along with deregulating the cell cycle and DNA repair genes, perhaps indicating properties akin to an oncogene." (PMID 33809117, 2021). "We observed lower levels of CYP26A1 mRNA expression in the oral and pharynx tumor tissues." (PMID 33233443, 2020). "In contrast, increased induction of CYP26A1 may be detrimental for the anti-tumor action of ATRA, as the enzyme metabolizes and inactivates the retinoid." (PMID 25888236, 2015).
tumor (continued). "Therefore, future studies are warranted to better understand the regulatory mechanism of CYP26A1 overexpression and its molecular impact on the neoplasia of human malignancy in the cervix, head, and neck." (PMID 25294402, 2014). "Furthermore, the induction of CYP26A1 mRNA in SH-SY5Y tumours in response to 13cisRA was potentiated by co-treatment with R116010." (PMID 17486130, 2007). "Our data also showed that metformin suppressed the Cyp26a1 enzyme, leading to an increase in all‐trans‐retinoic acid (atRA) levels, and reducing CD8+ T‐cell infiltration and proinflammatory/pro‐tumour cytokines secreted by CD8+ T cells." (PMID 37997519, 2023). "Meanwhile, RT-qPCR assays revealed that ALDH6A1, FBP1, HAO2 and PSAT1 were markedly under-expressed in tumor tissues in exceeding 60% cases, and that TYMP, HK3, P4HA3, IL4I1, CYP26A1 and CPT1B were over-expressed in tumor tissues in exceeding 70% cases." (PMID 32737333, 2020). "We also successfully demonstrated the elevated CYP26A1 expression in HNC patients and its significant correlation with primary tumor growth." (PMID 25294402, 2014). "In ~70% of the time, hypermethylation of four of these promoters (RASSF1A, CYP26A1, KCNAB1 and SNCA) was detected in adjacent tissues whenever these genes were found to be hypermethylated in the primary tumor by qMSP." (PMID 20226036, 2010). "Previous studies in HCC have shown that CYP26A1 mRNA is downregulated in tumor tissue compared to paired-matched non-tumor tissues, but the role of CYP26A1 in HCC is not entirely clear despite being reported as hypovitaminosis." (PMID 38396873, 2024). "Compared with their adjacent noncancerous tissues, tumor tissues exhibited the consistent downregulation mRNA of CYP26A1 and CYP26B1 in patients number 2, 3, 5, and 6 (expression >2-fold change in numbers 2, 3, and 5)." (PMID 25839051, 2015). "In addition, this report is the first to demonstrate the increased expression of CYP26A1 in HNC and its significant correlation with primary tumor growth." (PMID 25294402, 2014). "In addition, we observed increased expression of CYP26A1 in HNC patients and its significant correlation with primary tumor growth." (PMID 25294402, 2014). "This suggests that decreasing the intracellular metabolism of ATRA, by inhibiting CYP26A1 activity using liarozole, might be a way to increase ATRA levels and augment RA signaling in tumor cells, including the reduction in tumor SC numbers in APC-mutant tissues." (PMID 34299349, 2021). "Thus, an increase in CYP26A1, due to increased ATRA degradation, provides a mechanism that explains the resistance of ApcMin/+ mice to ATRA treatment, and the failure of ATRA to prevent tumor development." (PMID 34299349, 2021). "The correlation between the RNA-seq and the tumour data was not as straightforward for CYP26A1." (PMID 28187790, 2017). "Furthermore, CYP26A1 expression was not significantly different in tumours from animals treated with R116010 prior ATRA." (PMID 17486130, 2007). "However, CYP26A1 expression in tumours from animals treated with 13cisRA in combination with two doses of R116010 at 2.5 mg kg−1 increased 4- to 20-fold in individual animals, compared to CYP26A1 expression after treatment with 13cisRA alone (data not shown)." (PMID 17486130, 2007).
infection (8 papers, 2012 to 2023). The state of being infected such as from the introduction of a foreign agent such as serum, vaccine, antigenic substance or organism. "We validated in two cell-lines (Caco-2 and HT-29) the changes in expression of a number of genes (MT1E, NPPB, NOTCH3, CYP26A1, HEY1 and CYP1A1) found to be differentially expressed using RNAseq following infection with C. concisus UNSWCD or BAA-1457." (PMID 27677841, 2016).
CYP26A1 also shares sentences with these, for which no sentence is quoted: acne (2 papers); leukaemia (2); psoriasis (2); 22q11.2 deletion syndrome (1); acute myeloid leukemia (1); asthma (1); cervical squamous cell carcinoma (1); Chiari malformation type II (1); cholestasis (1); Cirrhosis (1); diabetes (1); Flavivirus Infections (1); Genetic Disease (1); head and neck squamous cell carcinoma (1); Hypertelorism (1); Hypertension (1); learning disabilities (1); liver cancer (1); Lyme borreliosis (1); lymph node metastasis (1); melanoma (1); nervous system diseases (1); pharynx (1); prostate carcinoma (1); Stroke (1); type 1 diabetes (1).